TGM1 (transglutaminase 1)
Diseases named in the same sentence as TGM1 in open-access papers (continued):
Sharing a sentence is not in itself a finding about the gene and the disease.
metastatic melanoma (3 papers, 2021 to 2025). A melanoma that has spread from its primary site to another anatomic site. "Beyond E-cadherin, we observed enrichment of proteins that preferentially associate with nonpalmitoylated CTNND1, including filaggrin (FLG), plakophilin-1 (PKP1), and transglutaminase 1 (TGM1), all linked to poor clinical outcomes in metastatic melanoma." (PMID 41321310, 2025).
ovarian carcinoma (3 papers, 2019 to 2024). A malignant neoplasm originating from the surface ovarian epithelium. "However, in 206008_at cohort, increased expression of TGM1 linked to favorable OS of ovarian cancer, contrary to TCGA cohort." (PMID 31794425, 2019). "Subsequently, we introduced the ovarian cancer data other than TCGA to further assess the survival effects of GJB2, S100A2, SPOCK2 and TGM1 on prognosis (OS) by Kaplan-Meier plotter." (PMID 31794425, 2019). "Results show ERα occupancy in HOXB3, TGM1, TWIST2, and WT1 gene promoters, which are all relevant for ovarian cancer, and DOT1L co-binding with ERα only in the TWIST2 and WT1 promoter regions." (PMID 31689915, 2019).
Palmoplantar keratoderma (3 papers, 2016 to 2024). Abnormal thickening of the skin of the palms of the hands and the soles of the feet. "Despite the presence of the TGM1 variant, the CIE phenotype, which was initially characterized by palmoplantar keratoderma, ectropion, and large scaling on the trunk and the face, evolved in SICI with normal skin in this patient." (PMID 38791074, 2024). "Our findings showed that palmoplantar keratoderma was associated with NIPAL4, TGM1, CYP4F22 mutations and CERS3 deletion, but with varying severity." (PMID 34983512, 2022). "Yellowish severe keratoderma was found to be associated with NIPAL4 variations and brachydactyly to TGM1 mutations." (PMID 34983512, 2022).
Stroke (3 papers, 2022 to 2024). Sudden impairment of blood flow to a part of the brain due to occlusion or rupture of an artery to the brain. "Stroke was also the main effect in increasing the anti-inflammatory A2 astrocyte markers: Cd14 and Clcf1, whereas Tgm1 was only increased in HT + Stroke vs HT + Sham (P < 0.05)." (PMID 38886874, 2024). "In contrast, stroke-induced genes (Clcf1, Tgm1, S100a10) showed a transient increase at 3 days that was reduced by 7 days." (PMID 35350551, 2022). "Overall, the key significantly upregulated genes based on FC values were Cyp2a5, Tgm1, and Lcn2 (2.4, 4.57, and 4.26 folds, respectively), whereas downregulated genes were Prl, Hcrt, and Pou4f2 (−4.35, −3.3, and −6.1 folds, respectively), at pre-, post-stroke day 1 and day 3, respectively." (PMID 37175797, 2023).
eczema (2 papers, 2008 to 2016). "TGM1, which is localized in a chromosomal region (14q12) previously linked to eczema, was among the epidermal differentiation genes found to be over-expressed in lesional AE skin as compared to healthy skin." (PMID 19107207, 2008).
Sepsis (2 papers, 2024 to 2025). Sepsis is defined as life-threatening organ dysfunction caused by a dysregulated host response to infection. "TGM1 deficiency causes severe keratinization defects and skin barrier impairment (leading to metabolic disorders, growth delay, and bacterial infections), with severe cases risking potentially fatal sepsis." (PMID 41155269, 2025).
tauopathies (2 papers, 2020 to 2021). "TGM1 expression is closely associated with tauopathies and corpora amylacea formation in damaged, degenerating neurons." (PMID 33054763, 2020).
virus infection (2 papers, 2022 to 2025). "Both Akata virus infection and AG876 virus infection decrease the expression levels of numerous different differentiation markers induced by methylcellulose suspension in uninfected NOKs, including K10, involucrin, GHRL3, ZNF750, KLF4, TGM1 and SPRR1A." (PMID 36190982, 2022).
Adrenocortical carcinoma (1 paper, 2024). "In terms of OS, we observed a significant association between high expression of TGM1 and poor prognosis in several cancer types, including KIPAN, KIRC, Adrenocortical carcinoma (ACC), Skin Cutaneous Melanoma (SKCM), LIHC, and Pheochromocytoma and Paraganglioma (PCPG)." (PMID 38472489, 2024).
bladder cancer (1 paper, 2024). "Our findings revealed that TGM1 mRNA levels were significantly upregulated in 12 tumors, including bladder cancer, when compared to their corresponding normal tissues." (PMID 38472489, 2024).
chronic periodontitis (1 paper, 2019). A chronic inflammatory process that affects the tissues that surround and support the teeth. "In short, when MMP-2 and -9 and transglutaminase-1–3 were analyzed in 22 patients with chronic periodontitis and healthy controls, transglutaminase-1 and 3 mRNA levels in chronic periodontitis patients were lower than those in healthy controls." (PMID 31336777, 2019).
colitis (1 paper, 2021). Inflammation of the colon. "Here we show for the first time that an algal produced TGF- β mimic, TGM1, acts in a similar manner to mammalian expressed TGM1 and limits disease intensity and lymph node inflammation when given orally in mouse model of colitis." (PMID 34390759, 2021). "When delivered orally to mice, the algal expressed TGM1 is able to ameliorate weight loss, lymphadenopathy, and disease symptoms in a mouse model of DSS-induced colitis, demonstrating the potential of this biologic as a novel treatment of IBD." (PMID 34390759, 2021). "We have now expressed an active novel anti-inflammatory cytokine TGM1 in C. reinhardtii and further show that the algal TGM1 when given orally is able to regulate immune cells and protect mice from DSS colitis weight loss." (PMID 34390759, 2021). "Although TGM1 given to mice at steady-state tended to increase Treg numbers, a different outcome was observed in the DSS colitis model." (PMID 34390759, 2021).
diffuse large B-cell lymphoma (1 paper, 2024). "Additionally, TGM1 expression levels in Lymphoid Neoplasm Diffuse Large B-cell Lymphoma (DLBC) and THYM are correlated with age." (PMID 38472489, 2024).
esophageal cancer (1 paper, 2024). A primary or metastatic malignant neoplasm involving the esophagus. "According to xiantao database, PPL, PI3, LCE3E, and TGM1 were more expressed in esophageal cancer than normal tissues (p < .05)." (PMID 38241178, 2024).
head and neck squamous cell carcinoma (1 paper, 2024). A squamous cell carcinoma that arises from any of the following anatomic sites: lip and oral cavity, nasal cavity, paranasal sinuses, pharynx, larynx, and salivary glands. "There are significant differences in TGM1 expression in different clinical stages and grades of Head and Neck squamous cell carcinoma (NHSC)." (PMID 38472489, 2024).
hypohidrosis (1 paper, 2023). diminished sweating in response to appropriate stimuli. "Obstruction of sweat glands and hypohidrosis was reported for patients carrying mutations of TGM1." (PMID 36768511, 2023).
inflammatory bowel disease (1 paper, 2021). A spectrum of small and large bowel inflammatory diseases of unknown etiology. "The discovery of the immune suppressive protein, TGM1, which mimics TGF-β, from a helminth parasite which itself can suppress intestinal inflammation, led us to test the ability of recombinant TGM1 to inhibit inflammatory bowel disease in the well-characterized mouse model of DSS." (PMID 34390759, 2021).
nasal polyps (1 paper, 2024). "Conversely, the connection between the expression of TGM1 isoforms in the airway epithelium and allergic conditions like asthma and chronic rhinosinusitis with nasal polyps (CRSwNP) has been well documented." (PMID 39408635, 2024). "It has been shown that TGM1 is expressed and colocalized with tissue eosinophils, involving the maintenance and development of nasal polyps through fibrin polymerization." (PMID 39408635, 2024).
non-small cell lung carcinoma (1 paper, 2020). A group of at least three distinct histological types of lung cancer, including non-small cell squamous cell carcinoma, adenocarcinoma, and large cell carcinoma. "Other studies have found that high expression of TGM1 in non-small-cell lung cancer may be conducive to stable adhesion between cancer cells." (PMID 32546690, 2020).
Palmoplantar hyperkeratosis (1 paper, 2019). Abnormal thickening of the skin localized to the palm of the hand and the sole of the foot. "Furthermore, all Saudi Arabian patients showed palmar hyperlinearity but only TGM1 and ABCA12 affected individuals presented palmoplantar hyperkeratosis, while NIPAL4 and CYP4F22 presented only plantar keratosis." (PMID 30600594, 2019).
prion disease (1 paper, 2022). A transmissible disease that is caused by a protein that is able to induce abnormal folding of normal cellular proteins, leading to characteristic spongiform brain changes, which are associated with neuronal loss without an inflammatory response. "Furthermore, key enzymes and transporters, such as transglutaminase 1 (Tgm1) and ATP binding cassette subfamily A member 1 (ABCA1) that have been implicated in the clearance of misfolded protein, were up-regulated in murine prion disease." (PMID 36378750, 2022).
pulmonary fibrosis (1 paper, 2020). Chronic progressive interstitial lung disorder characterized by the replacement of the lung tissue by connective tissue, leading to progressive dyspnea, respiratory failure, or right heart failure. "Concordantly, the genes encoding transglutaminases (TGM1, TGM2 and TGM5), which are enzymes responsible for crosslinking and also involved in pulmonary fibrosis, were significantly upregulated." (PMID 32698440, 2020).
thymoma (1 paper, 2024). A neoplasm arising from the epithelial cells of the thymus. "in terms of PFI, we observed a significant correlation between high expression of TGM1 and poor prognosis in patients with KIPAN, KIRC, ACC, STES, LIHC, Stomach adenocarcinoma (STAD), and BCLA and low expression of TGM1 was associated with poor prognosis in patients with GBMLGG and Thymoma (THYM)." (PMID 38472489, 2024).
tumor (11 papers, 2017 to 2026). "We examined the correlation between TGM1 expression and prognosis, clinical characteristics, tumor heterogeneity, gene mutation, and immune infiltration in pan-cancer patients." (PMID 38472489, 2024). "The expression difference and prognosis of TGM1 were examined, along with its correlation with tumor heterogeneity, stemness, mutation landscape, and RNA modification." (PMID 38472489, 2024). "Additionally, TGM1 is linked to immune responses within the tumor microenvironment, which potentially impacts the effectiveness of immunotherapy." (PMID 39408635, 2024). "Notably, tumor cells exhibit unlimited proliferation when cellular homeostasis is disrupted, making the gene TGM1, which is associated with cell proliferation and keratinization, a potential breakthrough in tumor therapy." (PMID 38472489, 2024). "Consistent with the results in menadione-treated 293 T cells, menadione treatment resulted in a significant increase in the ectopic expression of TGM1 on the surface of tumor cells and significantly increased the cytotoxicity of γδ T cells to tumor cell lines." (PMID 39939816, 2025). "We also examined TGM1 expression in tumor tissues and tumor cell lines and found that ectopic expression of TGM1 was upregulated in some tumor tissues and some tumor cell lines." (PMID 39939816, 2025). "Our study revealed that the expression of TGM1 in normal tissues of KIRC is higher compared to tumor tissues." (PMID 38472489, 2024). "To investigate the relationship between TGM1 expression and tumor-infiltrating immune cells in the TME, we utilized the TIMER method to evaluate the infiltration score of different cell types." (PMID 38472489, 2024). "Our findings indicate that the expression of TGM1 plays a crucial role in tumor immunity within the TME." (PMID 38472489, 2024). "We further investigated the correlation between the expression level of TGM1 and tumor heterogeneity and stemness." (PMID 38472489, 2024). "The results from Timer analysis demonstrated a positive correlation between TGM1 expression and the infiltration of several immune cell types in the tumor microenvironment (TME) of PRAD, LIHC, LUAD, and BRCA." (PMID 38472489, 2024). "Knockdown of TGM1 in cancer cells has been shown to enhance apoptosis, indicating its involvement in tumor progression." (PMID 39408635, 2024). "Additionally, PPL and TGM1 levels were correlated with N status in both tumor and margin samples, respectively." (PMID 41695373, 2026). "TGM1 levels in tumor and margin samples were correlated in patients with concomitant diseases." (PMID 41695373, 2026). "However, in tumor tissue, TGM1 and KRT8 levels showed a statistically significant association with T status." (PMID 41695373, 2026). "Taken together, these findings confirmed that TGM1 could be ectopically expressed on the surface of tumor cells and cells after menadione treatment and serve as a ligand for Vδ2 γδ T-cell activation and cytotoxicity." (PMID 39939816, 2025). "We also investigated the prognostic value of TGM1 by analyzing tumor OS and PFI." (PMID 38472489, 2024). "Our study demonstrates that the role of TGM1 in tumors is not limited to a single tumor type." (PMID 38472489, 2024). "This suggests that the expression of TGM1 may be influenced by epigenetic regulation triggered by heterogeneity during tumor development or metastasis." (PMID 38472489, 2024). "Moreover, our findings are based on public database analysis and encompass multiple tumor types, necessitating further experiments to elucidate the mechanism of TGM1." (PMID 38472489, 2024). "Additionally, the relationship between TGM1 expression and tumor immunity was investigated using the TIMER method." (PMID 38472489, 2024). "In our analysis of tumor stemness, we observed a negative correlation between the expression level of TGM1 in LIHC and all six tumor stemness." (PMID 38472489, 2024). "In LICH, we found a negative correlation between TGM1 expression and 6 indicators of tumor stemness." (PMID 38472489, 2024).
tumor (continued). "Moreover, we could identify by transcriptome analysis several molecular markers involved in chemoresistance (TGM1, HSPAs, MT1s), cell‐adhesion and cell barrier (PKP3, CLDNs, PPL) that might help us to better understand the special characteristics of ascites‐derived tumor spheroids." (PMID 34060699, 2021).
cancer (8 papers, 2019 to 2024). A tumor composed of atypical neoplastic, often pleomorphic cells that invade other tissues. "Our findings indicated that the expression levels of TGM1 in various cancer types were associated with multiple immune regulatory genes and immune checkpoint (IC) genes." (PMID 38472489, 2024). "Furthermore, the regulation of TGM1 also influenced cancer cell sensitivity to chemotherapeutic drugs and the underlying mechanism may involve Wnt signaling pathway." (PMID 32076707, 2020). "The objective of this study is to perform a comprehensive analysis across various types of cancer to determine the prognostic significance of TGM1 in tumors and investigate its role in the immune environment." (PMID 38472489, 2024). "Nevertheless, our pan-cancer analysis of TGM1 provides a solid foundation and novel insights for future research." (PMID 38472489, 2024). "As a result, TGM1 is being investigated as both a prognostic marker and a therapeutic target for cancer treatment." (PMID 39408635, 2024). "Among these genes, only expression levels of GJB2, S100A2, SPOCK2 and TGM1 were significantly upregulated in cancer samples and their high expression indicated poor prognosis (OS or RFS)." (PMID 31794425, 2019). "Notably, high expression levels of TGM1 correlate with a poor prognosis in several cancers, including skin cutaneous melanoma, whereas in some cases, such as in Glioma (GBMLGG), TG1 appears to act as a protective factor." (PMID 39408635, 2024). "A pan-cancer analysis using data from The Cancer Genome Atlas (TCGA) revealed a significant correlation between TGM1 expression and the infiltration of CD4+ T cells, CD8+ T cells, neutrophils and dendritic cells in Bladder Urothelial Carcinoma and Breast Invasive Carcinoma." (PMID 39408635, 2024). "TGM1, which belongs to the transglutaminases (TGM) family, was demonstrated to be involved in cancer initiation and progression." (PMID 32076707, 2020).
infection (7 papers, 2009 to 2025). The state of being infected such as from the introduction of a foreign agent such as serum, vaccine, antigenic substance or organism. "A few persistent cutaneous fungal infections in LI have been documented, but those are rare cases, and little is known about the frequency of infection in ARCI patients with TGM1 mutations." (PMID 27442430, 2016). "This aligns with their ability to upregulate key skin barrier genes, including FLG, TGM1, and AQP3, which fortify the cornified envelope to prevent water loss and infection, while boosting hydration via water and glycerol transportation." (PMID 40283895, 2025). "The gene set related to cell differentiation included 10 DE genes, of which the skin barrier gene TGM1 (transglutaminase 1) showed the highest mRNA expression levels (22.3-fold) after infection." (PMID 19196461, 2009).
skin disorder (2 papers, 2016 to 2022). Any deviation from the normal structure or function of the skin or subcutaneous tissue that is manifested by a characteristic set of symptoms and signs. "It is interesting that many of the changes in gene expression found in HaCaT-IKKα skin equivalents are relative to genes involved in the development of different skin disorders (CNFN, CDSN, TGM1, ALOX12B, etc)." (PMID 27732959, 2016).
brain disorder (1 paper, 2023). A disease affecting the brain or part of the brain. "Challenges ahead will be to investigate the roles and function of TGM1, TGM2, ATF3, RCN3, ORAI1, and ITPR3 in TBI as well as TBI-induced secondary brain disorders." (PMID 37645012, 2023).
inflammation (1 paper, 2025). Aberrant reaction of the microcirculation characterized by movement of fluid and leukocytes from the blood into extravascular tissues. "The prototypic member, TGM1, induces in vitro differentiation of Foxp3+ T regulatory cells and attenuates airway allergic and intestinal inflammation in animal models." (PMID 40302223, 2025).
TGM1 also shares sentences with these, for which no sentence is quoted: Harlequin ichthyosis (4 papers); ichthyosis vulgaris (3); bacterial infection (2); breast carcinoma (2); congenital ichthyosiform erythroderma (2); Parkinson's (2); peeling skin disease (2); adenocarcinoma (1); airway allergy (1); amyotrophic lateral sclerosis (1); asthma (1); atopic dermatitis (1); bathing suit ichthyosis (1); bleeding disorder (1); brachydactyly (1); cervical cancer (1); chronic rhinosinusitis (1); congenital hypothyroidism (1); dermatitis (1); epidermolytic ichthyosis (1); Huntington disease (1); hypothyroidism (1); ichthyosis linearis circumflexa (1); ischemic stroke (1); leishmaniasis (1); Lewy Body disease (1); liver carcinoma (1); Lymphadenopathy (1); lymphoid neoplasm (1); malaria (1).
A further 15 diseases each share a sentence with TGM1 in 1 paper.